RNU1-74P (RNA, U1 small nuclear 74, pseudogene)
Gene: Small nuclear RNA gene on chromosome 1 (232,832,017 to 232,832,187, reverse strand). Ensembl gene ENSG00000206835.
Homologues: Orthologues: chimpanzee U1 (96% identical), macaque U1 (88% identical), rabbit U1 (75% identical). Paralogues in human: RNU1-89P (85% identical), RNU1-1 (85% identical), RNU1-2 (85% identical), RNU1-27P (85% identical), RNU1-28P (85% identical), RNU1-3 (85% identical), RNU1-4 (85% identical), RNVU1-18 (85% identical), RNVU1-29 (85% identical), U1 (85% identical), RNVU1-28 (84% identical), RNVU1-7 (84% identical), and 133 more.